OTUB1 (OTU deubiquitinase, ubiquitin aldehyde binding 1)
Diseases named in the same sentence as OTUB1 in open-access papers (continued):
Sharing a sentence is not in itself a finding about the gene and the disease.
cancer (continued). "Given the diverse implications of MMR in cancer development and therapy, OTUB1 could be a potential biomarker for diagnosis and intervention in MMR-associated cancers." (PMID 33640455, 2021). "CD44 expression suppressed ferroptosis in cancer cells in an OTUB1-dependent manner." (PMID 33540700, 2021). "The regulation of OTUB1 on cancer immunocyte infiltration was determined by the TIMER database." (PMID 33240928, 2020). "OTUB1 not only regulates cancer metastasis but also chemoresistance." (PMID 33537306, 2020). "The effects of OTUB1 in a variety of tumors reminds us that OTUB1 might play an important role during cancer evolution and some physiological activities." (PMID 33537306, 2020). "Recent studies have shown that OTUB1 plays a crucial role in tumorigenesis and cancer progression." (PMID 31737118, 2019). "OTUB1 is also an activator of a very important oncogene in cancer, RAS." (PMID 27516771, 2016). "Whereas down‐regulation or loss of function of RABEX5 in human cancers has not been reported, we found that OTUB1 expression is commonly up‐regulated in a substantial subset of NSCLCs harboring wt KRAS." (PMID 26881969, 2016). "In particular, high OTUB1 expression in cancer tissues indicated a poorer PFS and OS." (PMID 25431208, 2014). "Additionally, OTUB1 can regulate the stability of PD‐L1, thereby influencing cancer immune evasion." (PMID 40387552, 2025). "We further collected BLCA pathological specimens and para-cancer tissue for immunohistochemical staining of OTUB1 and β-catenin in our hospital, the results showed that the expression of OTUB1 and β-catenin was consistent, OTUB1 was closely related to β-catenin." (PMID 39113709, 2024). "Collectively, inhibiting OTUB1 may increase cancer sensitivity to conventional therapies." (PMID 38264570, 2023). "Collectively, inhibiting OTUB1 alone may have therapeutic effects in sensitive cancers." (PMID 38264570, 2023). "In addition, microRNA miR-542-3p, often downregulated in cancer, can target OTUB1 mRNA." (PMID 38264570, 2023). "In addition to immune regulation, OTUB1 has emerged as an important modulator in cancer." (PMID 37608493, 2023). "Secondly, OTUB1 might affect the cancer cell sensitivity to DNA damaging agents." (PMID 38264570, 2023). "For example, OTUB1 could promote cancer cell immunosuppression via stabilizing PD-L1." (PMID 36271031, 2022). "Moreover, OTUB1 plays a vital role in the pathogenesis and aggressive biology of cancers." (PMID 36339263, 2022). "Therefore, inhibition of Otub1 has been proposed as an anti-cancer therapeutic target." (PMID 33627137, 2021). "Furthermore, OTUB1 plays an increasingly important and irreplaceable role in the field of cancer." (PMID 33537306, 2020). "Given that both OTUB1 and SLC7A11 are upregulated in various cancers, dRib's action on this pathway suggests its potential as an anticancer agent." (PMID 41077887, 2025). "Total protein and RNA, extracted from these samples, were applied for western blot and RT-PCR assay for OTUB1 expression detection in BLCA tissue and para-cancer tissue." (PMID 39113709, 2024). "Among them, OTU Domain-Containing Ubiquitin Aldehyde-Binding Protein 1 (OTUB1) stands out as a critical member of the OTU deubiquitinating family, playing a pivotal role as a tumor regulator across various cancers." (PMID 39113709, 2024). "Our findings demonstrate that cathepsin K inhibition induces OTUB1 dephosphorylation-mediated Raptor destabilization through Syk-SHP2 activation leading to an increase in mitochondrial dysfunction and anti-cancer sensitivity." (PMID 37330581, 2023). "On the other hand, several deubiquitinating enzymes, including ubiquitin-specific peptidase 7 (USP7), USP22, OTUB1, and CSN5, stabilize PD-L1 protein in cancer cells." (PMID 38038129, 2023). "OTUB1, an OTU-family deubiquitinase, is a critical regulator of development, cancer, DNA damage response, and immune response." (PMID 38264570, 2023).
cancer (continued). "Nevertheless, the effect of OTUB1 on DEPTOR was shown in HEK293T and HeLa cells and the biological consequences in human cancer require further investigation." (PMID 38264570, 2023). "Intriguingly, OTUB1 is reported to stabilize SLC7A11 through CD44, which is known to be an important CSC marker in human cancers." (PMID 37726816, 2023). "As a result, OTUB1 silencing significantly suppressed HCT116 cellular survivability, while OTUB1 overexpression significantly enhanced cancer cell viabilities." (PMID 35354355, 2022). "OTUB1 (OTU deubiquitinase, ubiquitin aldehyde binding 1), which is overexpressed in a variety of human cancers, was shown to function as a major regulator for SLC7A11 stability." (PMID 35307036, 2022). "The depletion of endogenous OTUB1 reduces SLC7A11 expression and promotes ferroptosis in human cancer cells, which results in growth inhibition of human bladder cancer cell T24 mouse tumor xenografts." (PMID 36551253, 2022). "OTUB1 overexpression is frequently found in various human cancers, which maintains high expression of SLC7A11 in cancer cells by posttranslational regulation of OTUB1." (PMID 36552652, 2022). "For instance, previous study indicated that OTUB1 directly interacted with SLC7A11, which facilitated CD44-mediated effects on ferroptosis in human cancers." (PMID 35354355, 2022). "On the other hand, UBE2M and OTUB1 were negatively enriched in some cancer-related or immune response-related pathways, such as PI3K/AKT signaling in cancer, the JAK/STAT signaling pathway, pathways in cancer, and the chemokine signaling pathway." (PMID 35864871, 2022). "In 2019, it was shown that OTUB1 is a crucial controller of the activation and function of CD8 T-cells and Natural Killer (NK) cells in immune responses against cancer." (PMID 33800394, 2021). "For example, the cancer stem cell marker CD44 and the deubiquitinating enzyme OTU domain-containing ubiquitin aldehyde binding protein 1 (OTUB1) promote ferroptosis resistance through stabilizing SLC7A11." (PMID 33891303, 2021). "Genomic depletion of OTUB1 gene dramatically downregulates SLC7A11 expression and sensitizes cancer cells to ferroptosis." (PMID 34485285, 2021). "The deubiquitinase OTUB1 is often overexpressed in human cancers, and by stabilizing the cystine transporter SLC7A11, it replicates the ferroptosis process of cancer cells and promotes tumor development." (PMID 33574983, 2021). "At the molecular level, Otub1 stabilizes several oncoproteins such as Snail, and FOXM1 as a deubiquitinase that result in cancer cell proliferation and survival." (PMID 33627137, 2021). "Instead, OTU deubiquitinase ubiquitin aldehyde binding 1 (OTUB1) directly interacts with SLC7A11 and stabilizes SLC7A11 by deubiquitinating SLC7A11, and this interaction is tightly regulated by the cancer stem cell marker CD44." (PMID 33294126, 2020). "Additionally, OTUB1 and OTUB2 served as pivotal components in maintaining cancer stemness and promoting metastasis via deubiquitination and stabilization of YAP proteins in gastric and colon cancer, respectively." (PMID 40469292, 2025). "Similarly, OTUB1 stabilizes Snail, further facilitating the invasive characteristics of ESCC cells and underscoring its pivotal role in EMT and cancer progression." (PMID 39678489, 2024).
cancer (continued). "OTUB1 is the deubiquitinase OTU superfamily member and participates in multiple pathophysiological processes, including immunological response, ferroptosis, cancer development, and so on." (PMID 38315284, 2024). "Kyoto Encyclopedia of Genes and Genomes (KEGG) pathway analysis revealed that OTUB1 is involved in various important signaling pathways, such as transcriptional regulation, PI3K-AKT signaling pathway, cancer-related pathway, TGF-β signaling pathway, TNF pathway, Hippo signaling pathway and so on." (PMID 39113709, 2024). "Among these, OTU Domain-Containing Ubiquitin Aldehyde-Binding Protein 1 (OTUB1), a member of the OTU deubiquitination family, has emerged as a regulator influencing the development and progression of multiple cancers and immune-related disorders through various signaling pathways." (PMID 39113709, 2024). "Both studies found a correlation between OTUB1 and FOXM1 protein levels in cancer samples." (PMID 38264570, 2023). "Interestingly, replenished CCN6 markedly reduced the migration of OTUB1−/− 4T1 cells, indicating that OTUB1 influences cancer cell migration by regulating CCN6." (PMID 37608493, 2023). "Therefore, OTUB1 plays a critical role in stabilizing SLC7A11 and regulates CD44 (cancer stem cell marker)-mediated effects on ferroptosis to promote the development of human cancers." (PMID 37190313, 2023). "Several E3 ligase (Cullin3-SPOP, c‐Cbl, and β-TrCP) and deubiquitinases (CSN5, USP9X, USP21, OTUB1, and USP22) have been reported to regulate PD-L1 protein degradation in cancer cells, indicating posttranslational modification plays an important roles in regulation of PD-L1 stability." (PMID 34741014, 2021). "Notably, overexpression of the cancer-stem-cell-marker CD44 enhanced the stability of SLC7A11 by promoting the interaction between SLC7A11 and OTUB1; the depletion of CD44 partially abrogated this interaction." (PMID 33540700, 2021). "Moreover, mice deleted for the deubiquitinase Otub1 showed potentiated anti-cancer NK and CD8 cell responses, which allows us to identify Otub1 as a crucial regulator of NK and CD8 cell homeostasis, due to its role in IL-15R signaling transduction." (PMID 31614928, 2019). "The ability of OTUB1 to deubiquitinate SRPX2 in an acetylation-dependent manner suggests that protein acetylation may play a critical role in modulating the effects of circRNAs and deubiquitinating enzymes on cancer progression." (PMID 39333496, 2024). "On the other hand, several ubiquitin-specific peptidases, including USP7, USP22, OTUB1, and CSN5, regulate PD-L1 protein expression in an opposing fashion through removal of the polyubiquitin modification from PD-L1 and consequently protect PD-L1 from proteasomal degradation in cancer cells." (PMID 38038129, 2023). "Notably, OTUB1 seems to be involved in some cancer progression or other pathogenesis by acting as a nonenzyme." (PMID 36822329, 2023). "Besides OTUB1, other DUBs, such as USPs family (USP1, USP7, USP8, USP15, USP22), OTUs family (OTUD7B, OTUD6B, A20, and OTUB2) and other DUBs have been identified to regulate the progression of various cancers and applied for clinical cancer therapy." (PMID 35715413, 2022). "However, similar to OTUB1, UBE2M is widely reported to play an oncogenic role in cancers." (PMID 35864871, 2022). "Moreover, OTUB1 also participated in promotion of PD-L1 stability via hindering the degradation of PD-L1 through the ERAD pathway in tumor cells and subsequently enhanced cancer immunosuppression." (PMID 35354355, 2022). "Thus, inhibition of OTUB1 may blunt c-MYC activity, making it a promising target for cancer treatment." (PMID 35159073, 2022).
cancer (continued). "Likewise, several DUBs including DUB3, OTUB1, USP1, and USP27X have been reported to be capable of stabilizing Snail1 and promoting cancer progression, which also indicates the preference of Snail1 towards different DUBs within assorted cellular contexts and milieus." (PMID 32968046, 2020). "Therefore, we will explore whether OTUB1 affects the function of macrophages and other immune cells through RACK1 in HCC and its potential related mechanisms in our future studies to improve HCC patient outcomes in cancer immunotherapy." (PMID 38315284, 2024). "However, OTUB1 has thus far not been identified as a regulator of c-MYC, a proto-oncogene that is dysregulated in up to 70% of all cancers." (PMID 35159073, 2022).
tumor (74 papers, 2014 to 2026). "Depletion of OTUB1 reduces PD-L1, decreases PD-1 binding on tumor cells, and heightens tumor cell susceptibility to PBMC-mediated cytotoxicity." (PMID 40087690, 2025). "The deubiquitinase OTUB1, implicated as a potential oncogene in various tumors, lacks clarity in its regulatory mechanism in tumor progression." (PMID 38664499, 2024). "In multiple myeloma, OTUB1 promoted tumor survival by removing the K48-linked polyubiquitination chain from c-Maf to facilitate the transcription of oncogenes." (PMID 38315284, 2024). "A recent publication described a covalent small-molecule recruiter for the K48-ubiquitin chain-specific DUB OTUB1, which is actively involved in the stabilization of proteins associated with tumor progression such as KRAS." (PMID 36678835, 2023). "Results suggested that OTUB1 expression was associated with increased proliferation of CRC tumor cells." (PMID 35354355, 2022). "The deubiquitinating enzyme, OTUB1, has the ability to target various substrate proteins for degradation, many of which are associated with tumor development." (PMID 35494004, 2022). "Ovarian tumor associated proteinase-1 (OTUB1) is the first confirmed-member of the deubiquitinase ovarian tumor associated proteinase family (OTUs)." (PMID 34927544, 2021). "The marker genes of immune cells in ESCA tumor tissues are more susceptible to OTUB1 than those of immune cells in normal tissues." (PMID 33240928, 2020). "We will increase the number of patients to research the association between the expression of OTUB1 and per tumor stage in the future." (PMID 25431208, 2014). "The results revealed that the expression level of OTUB1 was significantly associated with tumor invasive depth (P =0.001), lymph node status (P =0.015), distant metastasis (P =0.013), and AJCC/TNM stage (P =0.003)." (PMID 25431208, 2014). "In line with in vitro findings, OTUB1‐deficient allografted tumours had reduced levels of CCN6." (PMID 37608493, 2023). "OTUB1 acts as a deubiquitinating enzyme that regulates ubiquitination and promotes the stabilization of tumorigenesis-associated proteins to participate in tumor progression." (PMID 36339263, 2022). "To further explore the association between the expression level of OTUB1 and tumor-infiltrating lymphocytes in different digestive cancers, we analyzed the effect of the copy number variation (CNV) of OTUB1 on the infiltration level of tumor-infiltrating lymphocytes." (PMID 33240928, 2020). "OTUB1 suppresses ferroptosis and maintains tumor cell survival by deubiquitinating and stabilizing key proteins like SLC7A11, GPX4, and p62." (PMID 42086528, 2026). "Talin2 is found to be stabilized via non‐canonical deubiquitination and direct interaction with ovarian tumor domain‐containing ubiquitin aldehyde‐binding protein 1 (OTUB1)." (PMID 40279639, 2025). "OTUB1 has been shown to directly interact with and stabilize the xCT transporter: knockdown of OTUB1 led to growth suppression of mice tumor xenografts and reduced activation of ferroptosis." (PMID 40114966, 2025). "OTUB1 demonstrates elevated expression levels across multiple tumor types and participates in cell cycle control and apoptotic regulation through protein degradation pathways." (PMID 40430059, 2025). "Downregulation of the deubiquitinase Otub1 significantly promotes tumor infiltration by T cells, enhancing anti-tumor immunity." (PMID 39223632, 2024). "OTUB1 expression level was positively correlated to pathologic and tumor stages and negatively correlated to overall survival." (PMID 38315284, 2024). "When sacrificing, the tumor volumes and weights indicated that OTUB1 knockdown greatly repressed the subcutaneous tumor formation." (PMID 38315284, 2024).